S1PR3 (sphingosine-1-phosphate receptor 3)
Diseases named in the same sentence as S1PR3 in open-access papers (continued):
Sharing a sentence is not in itself a finding about the gene and the disease.
lung carcinoma (9 papers, 2015 to 2026). "Transcriptomics analyses of EGFR TKI-resistant tumor models revealed an aberrant upregulation of S1PR3, which conferred enhanced metastatic potential to lung cancer." (PMID 42039707, 2026). "We previously demonstrated that S1P is involved in the exacerbation of the TLR9-induced inflammatory pathway associated to lung cancer, as well as in cell proliferation through a SPHK II/S1PR3 nuclear-dependent intracellular mechanism." (PMID 37176007, 2023). "In addition, the SK1/S1P/S1PR2 signaling pathway leads to imatinib resistance in chronic myeloid leukemia (CML), and the SK2/S1P/S1PR1/S1PR3 signaling pathway renders the A549 lung cancer cell line resistant to etoposide." (PMID 40069781, 2025). "We identify a hitherto unknown S1P/S1PR3 axis involved in the amplification of PBMC-driven inflammation through IL-6 release in lung cancer, likely explaining the involvement of S1P in lung cancer." (PMID 36010601, 2022). "Furthermore, in our previous studies, we have shown that circulating S1P is able to amplify lung cancer-associated inflammatory processes through the interaction of S1P with S1PR3 both in circulating peripheral blood mononuclear cells (PBMCs) and in lung cancer epithelial cells." (PMID 37446018, 2023). "We found that lung cancer tissues expressed mainly S1PR1, S1PR2 and S1PR3, whereas S1PR4 and S1PR5 were undetectable, probably because they are highly restricted to distinct cell types and tissues, such as the lymphoid tissues, brain, and spleen." (PMID 37446018, 2023). "Here, instead, we found that S1P activity was related to S1PR3 on circulating cells of lung cancer patients but not by TLR9 (data not shown)." (PMID 36010601, 2022). "Indeed, we demonstrated that S1PR1, S1PR2, S1PR3, and S1PR5, but not S1PR4 are correlated with worse lung cancer patient prognosis." (PMID 35897763, 2022). "The only significant correlation however was for S1PR3 that showed a positive correlation with the presence of cancer independent of COPD status, suggesting that the findings in COPD subjects in our study were not influenced by the presence of lung cancer." (PMID 26485657, 2015).
osteosarcoma (9 papers, 2020 to 2025). A usually aggressive malignant bone-forming mesenchymal neoplasm, predominantly affecting adolescents and young adults. "This study explores S1PR3 as a potential therapeutic target in osteosarcoma, the most common primary bone malignancy, which we have previously demonstrated to secrete S1P within the acidic tumor microenvironment." (PMID 40137142, 2025). "S1P has been demonstrated to enhance VEGFa gene expression in ECs and osteosarcoma cells, and S1PR3 to promote bone matrix formation and mineralization in OBs,17 respectively." (PMID 38477738, 2024). "For example, S1PR3 was elevated in osteosarcoma and inhibited the phosphorylation of YAP, and promoted the nuclear translocation of YAP." (PMID 34326314, 2021). "The expression levels of LPAR1, LPAR6, S1PR1, and S1PR3 were relatively high in the osteosarcoma tumor tissues." (PMID 34302117, 2021). "S1PR3 signaling promoted aerobic glycolysis by the YAP/c-MYC/PGAM1 axis in osteosarcoma." (PMID 36361531, 2022). "Furthermore, they showed a synergistic inhibitory action of methotrexate and S1PR3 antagonist TY52156 on osteosarcoma cellular growth." (PMID 33920887, 2021). "Additionally, the S1P/S1PR3 axis plays a role in promoting cancer cell proliferation and aerobic glycolysis as well as inhibition of apoptosis by activating the YAP/c-MYC/phosphoglycerate mutase 1 axis in osteosarcoma cells." (PMID 35625898, 2022).
Anxiety (8 papers, 2016 to 2025). Intense feelings of nervousness, tension, or panic often arise in response to interpersonal stresses. "We elaborated on these findings by investigating whether pharmacologically inhibiting TNFα signaling could ameliorate the anxiety- and depression-like behavior caused by S1PR3 knock-down." (PMID 31316053, 2019). "Together, these results show that the increased anxiety-like and depression-like behavior displayed by rats with S1PR3 knock-down in the mPFC was due to elevated TNFα expression." (PMID 31316053, 2019). "Virally-mediated over-expression of S1PR3 in the mPFC produces a resilient phenotype whereas its knock-down produces a vulnerable phenotype, characterized by increased anxiety- and depressive-like behaviors, and these effects are mediated by TNFα." (PMID 31316053, 2019). "We reaffirmed that knock-down of S1PR3 in the mPFC (in iAAV-S1PR3-injected rats) increased anxiety-like behavior as assessed by decreased time interacting with the stimulus rat in the social interaction test compared to iAAV-scramble controls." (PMID 31316053, 2019). "Therefore, the increased anxiety-related and depression-related behaviors displayed by defeated S1PR3 knock-down rats was due, at least in part, to increased TNFα." (PMID 31316053, 2019). "When TNFα was also knocked-down at the same time as S1PR3, the increase in anxiety-like behavior was reversed but IL1β knock-down with knock-down of S1PR3 did not produce behavioral changes different from S1PR3 knock-down alone." (PMID 31316053, 2019). "In particular, the finding that S1PR3 mRNA correlated negatively with PTSD symptom severity may provide the groundwork for the development of treatment strategies targeting sphingolipid receptors for stress-related psychiatric disorders including PTSD, anxiety, and depressive disorders." (PMID 31316053, 2019).
Cerebral ischemia (8 papers, 2015 to 2024). Restriction of arterial blood supply to the brain associated with insufficient oxygenation to support the metabolic requirements of the tissue. "In the cerebral ischemia–reperfusion model, inhibition of S1PR3 improved the infarct volume and neuronal damage in mice after tMCAO." (PMID 35242008, 2022). "In summary, our results provide a new evidence that S1PR3 participates in the regulation of oxidative stress after cerebral ischemia and reperfusion and regulates brain damage after cerebral ischemia through regulation of nNOS/NO." (PMID 35242008, 2022). "We used the S1PR3 antagonist CAY-10444 to study the role of S1PR3 in cerebral ischemia and reperfusion to provide new methods for the treatment of stroke." (PMID 35242008, 2022). "The results of H&E, Nissl and FJC staining confirmed the point that S1PR3 mediates brain damage during cerebral ischemia and reperfusion." (PMID 35242008, 2022). "S1PR3, an S1P receptor, is upregulated after cerebral ischemia." (PMID 39159174, 2024). "Experimental verification revealed that S1PR3 expression increased after cerebral ischemia and may be involved in the regulation of BBB injury." (PMID 35685645, 2022). "In a previous KEGG analysis, we found that the MAPK signaling pathway and the PI3K-Akt signaling pathway may be important pathways regulating S1PR3 in cerebral ischemia injury." (PMID 35685645, 2022). "S1PR3 is expected to be an indicator and predictor of cerebral ischemia, and drugs targeting S1PR3 may also provide new ideas for clinical medications." (PMID 35685645, 2022). "The S1PR3-specific inhibitor CAY10444 was injected into the abdominal cavity of mice after cerebral ischemia/reperfusion (I/R) injury, and changes in the expression of blood–brain barrier-related molecules were measured using PCR, western blotting, and immunofluorescence staining." (PMID 35685645, 2022). "Then, we performed experimental verification of our results and finally found that S1PR3 participates in the destruction of the integrity of the BBB during cerebral ischemia and reperfusion injury and participates in the regulation of PI3K/Akt, p38MAPK, and ERK1/2 pathways." (PMID 35685645, 2022). "However, more experiments are needed to verify the role of S1PR3 in cerebral ischemia." (PMID 35685645, 2022). "Therefore, more research is needed to confirm whether S1P is an oxidative stress process regulated by S1PR3 during cerebral ischemia and reperfusion." (PMID 35242008, 2022). "In this article, we used the S1PR3-specific antagonist CAY-10444, evaluated the neurological scores and brain water content of mice after cerebral I/R, and finally explored whether S1PR3 is involved in the process of cerebral ischemia/reperfusion (I/R) injury by regulating BBB injury." (PMID 35685645, 2022). "In addition, we verified the results in the GSE22255 peripheral blood sequencing collection and found that S1PR3 was significantly upregulated in patients with IS and was a good IS indicator; therefore, S1PR3 can be used as a marker molecule for predicting cerebral ischemia." (PMID 35685645, 2022). "In the initial KEGG analysis, we also found that S1PR3 may participate in the MAPK signaling pathway, PI3K-Akt signaling pathway, and other pathways during cerebral ischemia and reperfusion injury." (PMID 35685645, 2022). "After the S1PR3 inhibitor CAY-10444 was administered to tMCAO mice, the MDA content in the brain tissues decreased significantly, and the SOD vitality increased, indicating that S1PR3 is involved in the regulation of cerebral ischemia and oxidative stress." (PMID 35242008, 2022). "Similarly, inhibition of S1PR3 can reduce the expression of NO synthase subtype neuronal NOS (nNOS) and reduce the production of NO after cerebral ischemia." (PMID 35242008, 2022).
Cerebral ischemia (continued). "We found that the expression of eNOS increased after cerebral ischemia and reperfusion, but inhibition of S1PR3 did not affect the expression of eNOS, suggesting that S1PR3 does not play a relevant role in regulating eNOS activity in the tMCAO model." (PMID 35242008, 2022). "After cerebral ischemia and reperfusion, the oxidative stress response was enhanced, and after the administration of the S1PR3 inhibitor, the SOD content increased and the MDA content decreased, indicating that S1PR3 plays an important role in regulating oxidative stress response." (PMID 35242008, 2022).
multiple sclerosis (8 papers, 2012 to 2025). A progressive autoimmune disorder affecting the central nervous system resulting in demyelination. "While drug development has prioritized S1P1 receptors—spurred by the non-specific S1P receptor agonist fingolimod (approved by the FDA in 2010 and EMA in 2011 for multiple sclerosis)—S1PR3’s established angiogenic role positions it as a compelling candidate for therapeutic exploitation." (PMID 40137142, 2025). "Accordingly, astrocytic S1PR1 and S1PR3 were upregulated in multiple sclerosis lesions." (PMID 37508508, 2023). "In addition, expression of S1PR1 and S1PR3 is increased in reactive astrocytes in multiple sclerosis lesions and in cultured astrocytes under proinflammatory circumstances." (PMID 31861214, 2019). "Alterations in the expression levels of S1PR isoforms have been demonstrated in other pathological states for instance upregulation of S1PR1 and S1PR3 and downregulation of S1PR2 were reported in multiple sclerosis lesions and in experimental asthma, respectively." (PMID 28493876, 2017). "Other S1P analogues exhibiting higher S1PR specificity than fingolimod (FTY720) include siponimod/BAF13 (a potent agonist of S1PR1 and S1PR5 but not of S1PR3), and RPC1063/ozanimod have entered phase III clinical trials for multiple sclerosis." (PMID 31861214, 2019).
depression (7 papers, 2019 to 2025). "S1PR3 mRNA was also inversely correlated with scores on the Beck Depression Inventory, suggesting that elevated S1PR3 expression was related to reduced symptoms of depression in these combat-exposed veterans." (PMID 31316053, 2019). "However, one study revealed that fingolimod increased stress resilience (i.e., prevented stress-evoked depression-like behavior) in a model of chronic unpredictable stress via activation of S1PR3 in the medial prefrontal cortex." (PMID 39177699, 2024). "Additionally, S1PR3 mRNA may be used as a screening tool for anti-inflammatory treatments of depression." (PMID 31316053, 2019). "One potential application of this work in humans is using S1PR3 as a biomarker for the diagnosis and treatment of PTSD and depression." (PMID 31316053, 2019).
Hypertension (7 papers, 2012 to 2023). The presence of chronic increased pressure in the systemic arterial system. "S1PR activation by fingolimod produced moderate hypertension (2‐3 mm Hg) in clinical setting and caused dose‐dependent hypertension by activating S1PR3 in rats." (PMID 32803879, 2020). "Therefore, the risk of adverse events related to vasoconstriction (hypertension, headache, and stroke) which may be associated with S1PR3 was predicted to be low." (PMID 36071831, 2022). "The inhibition of S1PR3 could also lead to hypertension, bradycardia, macular edema, reduced pulmonary function, hepatic adverse effects, and neoplasm." (PMID 38003272, 2023). "In addition, many adverse events, including hypertension, macular edema, pulmonary toxicity, and hepatotoxicity, have been associated with FTY720, because of its off-target interactions with other S1PRs subtypes, particularly with S1PR3." (PMID 32153401, 2020).
ischemic stroke (7 papers, 2021 to 2025). A stroke disorder caused by obstruction of blood flow to the brain, due to thrombotic (local blood clot formation) or embolic (due to a blood clot or other material traveling from another site) event. "S1PR3 worsens ischemic stroke by disrupting the blood–brain barrier via MAPK and PI3K-Akt pathways; its inhibition protects BBB integrity and improves outcomes." (PMID 40880849, 2025). "Lastly, we observed higher plasma S1PR3 concentrations in experimental stroke and in patients with ischemic stroke." (PMID 38868192, 2024). "S1P is the ligand protein for S1PR and has been identified to bind to S1PR1, S1PR2, and S1PR3 to trigger neuroinflammatory reactions in ischemic stroke." (PMID 35055089, 2022). "Here, we investigated the role of S1PR3 in ischemic stroke in rodent models and patient samples." (PMID 38868192, 2024). "Together, our results establish S1PR3 as a potential drug target and biomarker in ischemic stroke." (PMID 38868192, 2024). "Accumulating evidence demonstrated that S1PR3 influenced proinflammatory M1 polarization and activated the p38 MAPK pathway that is involved in the brain injury following ischemic stroke, and astrocytic S1PR3 modulated the blood‐tumor barrier via regulation of CCL2 secretion in brain metastases." (PMID 33645008, 2021). "S1PR3 affects pro-inflammatory M1 polarization and activates the p38 MAPK pathway, which is involved in brain injury after ischemic stroke." (PMID 38633536, 2024).
ovarian carcinoma (7 papers, 2014 to 2025). A malignant neoplasm originating from the surface ovarian epithelium. "This is evident since systemic administration of CAY10444, an S1PR3 antagonist, suppressed expression of angiogenic growth factors and neovascularization of a neoplasm in a mouse ovarian cancer model." (PMID 33199821, 2021). "We previously found that S1PR1, S1PR2 and S1PR3 were overexpressed in ovarian cancer tissue." (PMID 33931106, 2021). "Because S1PR1 and S1PR3 mediated S1P-induced angiogenic factor secretion in ovarian cancer cells, we wanted to determine whether they are responsible for the angiogenic potential of the cells." (PMID 29088837, 2017). "Indeed, S1P induced the angiogenic factor expression via S1PR1 and S1PR3 in ovarian cancer cells; in fact, blocking SphK or S1PR1/3 might functionally inhibit ovarian cancer angiogenesis." (PMID 36362323, 2022). "In ovarian cancer, we observed that 55% (11/20) samples displayed high S1PR1 level, 80% (16/20) samples showed high S1PR2 level and 75% (15/20) samples showed high S1PR3 level." (PMID 29088837, 2017). "SphK1 could control the release of S1P, which was able to promote the secretion of some proangiogenic cytokines in ovarian cancer cells via S1PR1 and S1PR3." (PMID 29088837, 2017). "The proliferation of ovarian cancer cells was not affected by S1PR3 inhibitor CAY10444 (1 μM)." (PMID 35242008, 2022). "Our results showed that down-regulation of S1PR1 or S1PR3, but not S1PR2, effectively inhibited S1P-induced VEGF, IL-8 and IL-6 secretion in ovarian cancer cells." (PMID 29088837, 2017). "We found that S1PR1 and S1PR3, but not S1PR2, were responsible for the angiogenic potential and angiogenic factor secretion of ovarian cancer cells in vitro." (PMID 29088837, 2017).
Stroke (7 papers, 2015 to 2024). Sudden impairment of blood flow to a part of the brain due to occlusion or rupture of an artery to the brain. "Increased Smyd2 impairs S1PR1 formation and induces S1PR3 production, which is detrimental to TJs and BBB dysfunction after stroke." (PMID 35297562, 2022). "Further, we find that administration of an S1PR3 antagonist at 4-h post-stroke, but not at later timepoints, improves stroke outcome." (PMID 38868192, 2024). "We show that S1PR3 is acutely upregulated in perilesional reactive astrocytes after stroke, and that stroke volume and behavioral deficits are improved in mice lacking S1PR3." (PMID 38868192, 2024).
asthma (6 papers, 2017 to 2025). "To evaluate the effect of VPC23019, S1PR1 and S1PR3 antagonist, on experimental asthma, we carried out histologic analyses of the bronchus at 24 h after the last challenge." (PMID 30192865, 2018). "The aim of this study is to evaluate the role of S1P and S1PR3 in the airway ECs using human bronchial EC lines and experimental asthma mouse models." (PMID 30192865, 2018). "Because suramin may block other receptors besides the P2R family (e.g., sphingosine-1-phosphate receptor-3), we used the ATP-hydrolyzing enzyme apyrase, which also reduced the airway inflammation of asthma, illustrating ATP has potential to promote the airway inflammation." (PMID 28626774, 2017). "For instance, PAD4 expression positively regulates NETs in severe asthma, and CEACAM1 influences NET formation by regulating the S1P-S1PR2/S1PR3 axis." (PMID 40452820, 2025). "In conclusion, S1P/S1PR3 pathway has a role in release of CCL20, which has a role in experimental asthma mouse model, from bronchial ECs." (PMID 30192865, 2018).
glioma (6 papers, 2013 to 2025). A benign or malignant brain and spinal cord tumor that arises from glial cells (astrocytes, oligodendrocytes, ependymal cells). "Then, VPC 23019, a S1PR1 and S1PR3 antagonist, was used to verify the roles of S1PRs on the anti-glioma effects of FTY720." (PMID 32194542, 2020). "In pediatric gliomas, while LGAT was found to overexpress S1PR3 to a slightly greater degree than HGAT, LGAT had comparatively lower overexpression of LAMA2 than that of HGAT." (PMID 40227800, 2025). "Collectively, with the minor exception of S1PR3 in pediatric tumors, BTB expression patterns suggested a more permeable phenotype in high-grade relative to low-grade gliomas." (PMID 40227800, 2025).
ischemia (6 papers, 2020 to 2025). A hypoperfusion of the BLOOD through an organ or tissue caused by a PATHOLOGIC CONSTRICTION or obstruction of its BLOOD VESSELS, or an absence of BLOOD CIRCULATION. "Murine studies showed that S1PR1 mediates the negative inotropic effects of S1P in the heart, whereas selective activation of S1PR3 mediated cardioprotection after ischemia/reperfusion injury." (PMID 41418457, 2025). "We found that endothelial markers (Angptl4), and pericyte marker (Cyp1b1, Emp1, S1pr3, Serping1, and Cxcl1) were upregulated in prolonged ischemia." (PMID 35154109, 2022). "In the mouse cerebral I/R model, S1PR3 expression increased 24 h after ischemia." (PMID 35685645, 2022).